BRCA2 (BRCA2 DNA repair associated)
Diseases named in the same sentence as BRCA2 in open-access papers (continued):
Sharing a sentence is not in itself a finding about the gene and the disease.
breast cancer (continued). "Common genetic variants contribute to the observed variation in breast cancer risk for BRCA2 mutation carriers; those known to date have all been found through population-based genome-wide association studies (GWAS)." (PMID 23544012, 2013). "Even though BRCA1 and BRCA2 account for the majority of genetic mutations found in breast cancer cases, only 5–10% of breast cancer cases result directly from specific gene mutations." (PMID 34589269, 2013). "Following the identification of BRCA2, we set off on a search for yet another high risk breast cancer gene, ‘BRCA3’." (PMID 23339072, 2013). "Pathogenic germline mutations in BRCA1 or BRCA2 are detected in less than one third of families with a strong history of breast cancer." (PMID 23704984, 2013). "The hazard ratios for the percentiles of the combined genotype distribution of loci associated with breast cancer risk in BRCA2 mutation carriers were translated into absolute breast cancer risks under the assumption that SNPs interact multiplicatively." (PMID 23544012, 2013). "Germline mutations in the two major susceptibility genes for breast cancer, namely BRCA1 and BRCA2, confer a 60–85% lifetime risk of breast cancer but account for only about 20% of familial breast cancer cases." (PMID 24040146, 2013). "BRCA1 and BRCA2 genes are the most commonly mutated genes, but additional genes associated with hereditary breast cancer are emerging." (PMID 23586058, 2013). "Approximately 2% of Ashkenazi Jews carry mutations in BRCA1 or BRCA2 that confer, at age 70, an estimated risk of breast cancer of 56%." (PMID 23855721, 2013). "Among them, PALB2 (partner and localizer of BRCA2) has emerged as a breast cancer susceptibility gene in several populations world-wide." (PMID 23941127, 2013). "In particular, in BRCA1 mutation carriers, the cumulative life time risk for breast cancer is about 70%; for ovarian cancer 40%; and, in BRCA2 mutation carriers, 50% for breast and 10% for ovarian cancer." (PMID 23644885, 2013). "All possible nucleotide substitutions were seen within 96 possible trinucleotide sequence contexts without predominant patterns of particular trinucleotides, which was a characteristic signature of both BRCA1- and BRCA2-associated breast cancers." (PMID 24265793, 2013). "For example, the BRCA2 gene belongs to a class of genes known as tumor suppressor genes and is the most well-known gene linked to breast cancer risk." (PMID 24267658, 2013). "Tumor suppressor breast cancer susceptibility gene 2 (BRCA2) is responsible for a large percentage of familial breast cancer cases." (PMID 23833673, 2013). "In 2011, AstraZeneca performed a proof of principal clinical trial on 54 subjects with BRCA1 or BRCA2 mutations with advanced breast cancer that were treated with PARP inhibitor olaparib." (PMID 23401782, 2013). "For example: familial breast cancer mutations in the BRCA2 gene, associated with a 3- to 10-fold increased risk of PC, account for increasing frequency and the highest proportion (5–17%) of known causes of inherited PC." (PMID 24303367, 2013). "Per allele hazard ratios (HR) and 95% confidence intervals (CI) of previously published breast cancer loci among BRCA2 mutation carriers from previous reports and from the iCOGS array, ordered by statistical significance of the region." (PMID 23544012, 2013). "BRCA1 mutations confer upon women a breast cancer risk of about 60% and an ovarian cancer risk of about 40%; BRCA2 mutations confer a breast cancer risk of about 50% and an ovarian cancer risk of about 20%." (PMID 23638402, 2013). "E3 Ubiquitin ligase; regulates cell cycle; expression of Fbxl7 variants correlate with increased risk of breast cancer in BRCA2 mutation carriers." (PMID 24255707, 2013). "Female BRCA2 mutation carriers face a lifetime risk around 26%–84% for breast cancer and 20% for ovarian cancer." (PMID 23586058, 2013).
breast cancer (continued). "Breast cancer hazard ratios (HR) and 95% confidence intervals (CI) of novel breast cancer loci with P-values of association <10−5 among BRCA2 mutation carriers." (PMID 23544012, 2013). "The names BRCA1 and BRCA2 stand for breast cancer susceptibility gene 1 and breast cancer susceptibility gene 2, respectively." (PMID 23401782, 2013). "SNPs in two additional regions had P-values<10−5 for breast cancer risk associations for BRCA2 mutation carriers." (PMID 23544012, 2013). "In conclusion, this meta-analysis suggests that RAD51 variant 135C homozygote is associated with elevated breast cancer risk among BRCA2 mutation carriers." (PMID 24040396, 2013). "For example, the identified rare variants in BRCA1 and BRCA2 gene all increase risk of breast cancer, and the four rare variants identified in IFIH1 gene all protect against type I diabetes." (PMID 23472070, 2013). "Inactivating mutations in cancer susceptibility genes, such as BRCA1 and BRCA2, which are inherited in an autosomal dominant pattern, are the major genetic factor associated with a high risk of breast cancer at an early age." (PMID 23469205, 2013). "BRCA1 and BRCA2 were significantly associated with mammary tumours and the association was stronger to BRCA1 in malignant tumours." (PMID 23738139, 2013). "BRCA1 and BRCA2 are clinically the most important genes associated with breast cancer susceptibility." (PMID 23941127, 2013). "Women with mutations in BRCA1 or BRCA2 are at high risk of developing breast cancer and, in British Columbia, Canada, are offered screening with both magnetic resonance imaging (MRI) and mammography to facilitate early detection." (PMID 23837641, 2013). "This meta-analysis suggests that RAD51 variant 135C homozygote is associated with elevated breast cancer risk among BRCA2 mutation carriers." (PMID 24040396, 2013). "This comprehensive update of novel and previously reported breast cancer susceptibility loci contributes to the establishment of a panel of SNPs that modify breast cancer risk in BRCA2 mutation carriers." (PMID 23544012, 2013). "A recent study of Scandinavian families also suggested the presence of a third human breast cancer susceptibility locus that is distinct from BRCA2, on the long arm of human chromosome 13." (PMID 24023717, 2013). "Among known predisposition genes, deleterious mutations in BRCA1 and BRCA2 confer the strongest effect on disease susceptibility and are associated with a lifetime risk of breast cancer of up to 85% for such mutation carriers." (PMID 24171766, 2013). "In agreement with our findings, SNP rs13281615 was associated with increased risk of breast cancer among people at higher risk (who have positive family cancer history or BRCA1/BRCA2 mutation)." (PMID 24171766, 2013). "DNA samples from 3,881 breast cancer affected and 4,330 unaffected BRCA2 mutation carriers from 47 studies belonging to the Consortium of Investigators of Modifiers of BRCA1/2 were genotyped and available for analysis." (PMID 23544012, 2013). "Two other loci, in ZNF365 (rs16917302) on 10q21 and a locus on 20q13 (rs311499), were also associated with breast cancer risk in BRCA2 mutation carriers with P-values<10−4 (P = 3.8×10−5 and 6.6×10−5, respectively)." (PMID 23544012, 2013). "BRCA1 and BRCA2 are the two main breast cancer susceptibility genes for which mutation recognition is important to assess cancer risk and to identify more suitable treatment strategies." (PMID 23354980, 2013). "We performed mutation screening of all coding and 3′ and 5′ UTR sequences of BRCA1 and BRCA2 genes on ten high risk breast cancer families." (PMID 24312913, 2013). "Female carriers of BRCA1 or BRCA2 mutations have a lifetime risk of 49 to 87% for developing breast cancer, wherefore they are offered intensive cancer surveillance as well as risk reducing surgery." (PMID 23704984, 2013).
breast cancer (continued). "Since then, analysis of BRCA2 has entered routine clinical genetics practice to diagnose women at high risk of developing breast cancer." (PMID 23339072, 2013). "For example, dysfunctional BRCA1 and BRCA2 diminish the efficiency of HR and germ line mutations in humans lead to a high incidence of breast cancer." (PMID 23443494, 2013). "These risks are comparable to the average breast cancer risk associated with carrying a BRCA2 mutation with penetrance to age 70 of 45% (95%CI 31 to 56)." (PMID 23448497, 2013). "For instance, women with a family history of breast or ovarian cancer with point mutations in the BRCA1 and BRCA2 genes are clinically recognized to have a high risk of developing breast cancer." (PMID 24358278, 2013). "Two of the BRCA2 mutations were found in a group of consecutive breast cancer patients with a frequency of 0.51% and 0.38%." (PMID 23767878, 2013). "A recent meta-analysis presented subgroup analyses considering BRCA1 and BRCA2 mutation carriers and found increased breast cancer risk for women with both alleles ≥29 repeat." (PMID 23483928, 2013). "Despite characterization of these genetic susceptibility genes, fewer than 10% of all breast cancers are attributable to mutations in BRCA1/BRCA2." (PMID 23922822, 2013). "Germline mutations in BRCA1 and BRCA2 are detected in up to 28% of these breast-cancer families; however, it is expected that mutations still remain undetected by the currently used screening methods." (PMID 23704984, 2013). "Rare deleterious mutations in other genes of this pathway, including BRCA1 and BRCA2, confer a high risk of breast cancer." (PMID 23544014, 2013). "The landscape of genetic risk factors for breast cancer is known to be diverse, ranging from rare high-risk alleles, like BRCA1 and BRCA2, to common polymorphisms that only confer a minor breast cancer risk increase." (PMID 23383274, 2013). "rs9348512 (6p24) is the first example of a common susceptibility variant identified through GWAS that modifies breast cancer risk specifically in BRCA2 mutation carriers." (PMID 23544012, 2013). "Further, FGFR2 expression in female breast cancer was highly correlated with ERα, PR expression and low grade, and with cancers in patients with a BRCA2 mutation." (PMID 23308200, 2013). "In fact, data from our own Inherited Cancer Registry (ICARE) at Moffitt indicated that of 253 female BRCA1 and BRCA2 mutation carriers, 127 had remaining at risk breast tissue (including 40 with a prior breast cancer diagnosis)." (PMID 26097796, 2012). "It is estimated that about 5–10% of ovarian and 2–5% of all breast cancer patients are carriers of a germline BRCA1 or BRCA2 gene mutation." (PMID 22395474, 2012). "A significant proportion occurs in families with a history of breast cancer and in particular those carrying BRCA2 mutations." (PMID 23146383, 2012). "Both BRCA1 and BRCA2 mutations have been found more often in patients with high grade breast cancer compared to age-matched control patients." (PMID 22736197, 2012). "We aimed to investigate the effect on splicing of the BRCA2 variants c.8488-1G > A (exon 20) and c.9026_9030del (exon 23), as well as 41 BRCA2 variants reported in the Breast Cancer Information Core (BIC) mutation database." (PMID 22632462, 2012). "According to the literature, 10% of ovarian cancer cases and 3–5% of breast cancer cases are associated with BRCA1 or BRCA2 mutations." (PMID 22737296, 2012). "It is difficult therefore to apply an exact multiple testing, but taken together, the gene expression and association results are suggestive for the involvement of this SNP in breast cancer risk for BRCA2 mutation carriers." (PMID 22513257, 2012). "Woman carrying mutations in either BRCA1 or BRCA2 have an 80 to 90% lifetime risk of developing breast cancer and a 20 to 50% chance of developing ovarian cancer." (PMID 23171648, 2012).
breast cancer (continued). "One SNP displayed a significant association with breast cancer in carriers of BRCA2 mutations at the 5% significance level." (PMID 22513257, 2012). "Four SNPs were associated with the risk of breast cancer for BRCA2 mutation carriers: rs10995190, P-trend = 0.015; rs1011970, P-trend = 0.048; rs865686, 2df-P = 0.007; rs1292011 2df-P = 0.03." (PMID 22348646, 2012). "Using these methods, we are now able to perform BRCA2 mutation analysis and search for abnormal BRCA2 splicing variants from mammary tumors in dogs, as is done in human cases." (PMID 22471976, 2012). "On the other hand, a recently published study accounted for 16% BRCA2 mutation of 115 male breast cancer cases from the United States, including 40% for breast cancer families and 13% for non-familial breast cancer." (PMID 22382806, 2012). "We have previously identified a BRCA1 or BRCA2 mutation in 2.3% of women with breast cancer using the same study population." (PMID 22455664, 2012). "In this study, we have used gene expression and genomic data to identify specific molecular features that distinguish tumors with BRCA2 mutations from tumors with other breast cancer predisposition mutations." (PMID 23284877, 2012). "In women, carriers of mutations in BRCA2, a tumor suppressor gene product, have a higher risk of breast cancer." (PMID 22471976, 2012). "Results of a phase II trial detailed how olaparib is effective in breast cancer patients with a BRCA1 or BRCA2 mutation and advanced disease." (PMID 22295252, 2012). "Germline mutations of the genes BRCA1 (breast cancer 1, early onset) and BRCA2 (breast cancer 2, early onset) are the most common cause of hereditary breast and ovarian cancer." (PMID 22809218, 2012). "BRCA1 and BRCA2 mutant carriers impose a highly increased risk for hereditary or familial breast cancer." (PMID 22937096, 2012). "When looking at all of the women in the trial, 41% of the BRCA1- or BRCA2-mutated breast cancer patients had an objective response when assigned 400 mg twice-daily olaparib." (PMID 22295252, 2012). "In humans, the breast cancer susceptibility gene, BRCA2, has been identified as a tumor-suppressor gene." (PMID 23071527, 2012). "The two high-penetrance genes most commonly mutated in HBOC are the tumor suppressor genes BRCA1 and BRCA2 (breast cancer, early onset 1 and 2)." (PMID 22655046, 2012). "In the United Kingdom, BRCA1 and BRCA2 mutations were identified in 5.9% of women diagnosed with breast cancer under the age of 36 years, and in 4.1% of women diagnosed with breast cancer between the age of 36 and 45 years." (PMID 22187038, 2012). "There are specific clinical and pathological features associated with hereditary BRCA1 or BRCA2 mutation associated breast cancers." (PMID 22382806, 2012). "We found one haplotype that was associated with higher expression of BRCA2, for which there is suggestive evidence that it is also associated with a protective effect for the development of breast cancer in BRCA2 mutation carriers." (PMID 22513257, 2012). "Genetic analyses, including detection of deleterious mutations, to identify carriers of BRCA2 mutation is strongly advocated as the lifetime risk of breast cancer is high (81–88%) for women carrying this mutation." (PMID 23071527, 2012). "Women carrying a BRCA2 mutation have a 50-60% lifetime risk of developing breast cancer and a 30% risk of developing ovarian cancer." (PMID 22737296, 2012). "We performed a systematic review of English Language Literature to determine the role of BRCA1 and BRCA2 gene mutations in African breast cancer patients." (PMID 23519070, 2012). "Genotyping of additional mutation carriers in the future will further clarify the involvement of this SNP in the penetrance of BRCA2 mutations in breast cancer." (PMID 22513257, 2012). "The prevalence of BRCA2 mutation in male breast cancer varies from 4 to 40% according to racial differences." (PMID 22382806, 2012).
breast cancer (continued). "Hereditary breast cancer is associated with mutations in genes such as BRCA1 and BRCA2 and accounts for 5%–10% of all breast cancer." (PMID 23227345, 2012). "Inherited mutations in two genes, breast cancer 1 (BRCA1) and BRCA2, are associated with a particularly striking increase in breast cancer risk." (PMID 23284877, 2012). "Nevertheless, this is also suggestive of an association between a higher expression haplotype of BRCA2 in mutation carriers with lower risk of developing breast cancer." (PMID 22513257, 2012). "In a recent study, it was suggested that the canine BRCA2 gene locus is associated with mammary tumors based on single nucleotide polymorphism analysis of an intronic marker." (PMID 22471976, 2012). "Breast-ovarian cancer (BOC)-causing mutations and other genetic variants are distributed along the entire coding and non-coding regions of BRCA1 and BRCA2, and more than 3400 gene variants have been described in the Breast Cancer Information Core (BIC)." (PMID 23961350, 2012). "The study suggested that family history is not a strong predictor of carrying a mutation in males and males who develop breast cancer should be screened for mutations in BRCA2." (PMID 22382806, 2012). "Throughout the continent of Africa, over a seventeen year period, 16 studies have evaluated 1150 patients for mutations in the BRCA1 and/or BRCA2 genes in breast cancer patients." (PMID 23519070, 2012). "Screening for BRCA2 mutations is widely performed in genetics laboratories to explain familial clustering of breast cancer." (PMID 23284877, 2012). "Pedigree analysis of clustered familial cases followed by positional cloning in the 1990s led to the discovery of tumor suppressor genes, BRCA1 and BRCA2, two major breast cancer susceptibility loci." (PMID 23107584, 2012). "Our study had a small number of male breast cancer patients and BRCA2 mutation was detected in only one (5.9%) patients." (PMID 22382806, 2012). "Carriers of mutations in the BRCA1 and BRCA2 genes are at very high risk of developing breast cancer (BC) and ovarian cancer." (PMID 22762150, 2012). "As a large proportion of MBCs are purported to arise in families with breast cancer and in particular BRCA2 mutation carriers, further description of this cohort is of significance in understanding and characterising the disease." (PMID 23146383, 2012). "The most prevalent genes causing this pathology are BRCA1 and BRCA2 (breast cancer early onset 1 and 2), which also predispose to other cancers." (PMID 22655046, 2012). "There were 5 (1.2%) of 429 known BRCA1 mutation carriers and 35 (10.3%) of 339 BRCA2 carriers who developed breast cancer." (PMID 23146383, 2012). "Nearly 3,500 different DNA variants of BRCA1 and BRCA2 have been reported at the Breast Cancer Information Core Database (BIC)." (PMID 22632462, 2012). "Unfortunately no data regarding BRCA germline mutations were available for both cohorts, but it seems probable that there is a higher rate of hidden BRCA2 mutation carriers in the male breast cancer group." (PMID 22765268, 2012). "Families with history of breast cancer have 50% increased risk of developing ovarian cancer due to germ line mutations in either BRCA1 or BRCA2 tumor suppressor genes." (PMID 22685544, 2012). "There was evidence of association with breast cancer risk for BRCA2 mutation carriers for four SNPs." (PMID 22348646, 2012). "Thanks to early multimodal screening, breast cancer in people carrying BRCA1 or BRCA2 mutations can be diagnosed at an early stage, with consequent favorable effects on their survival and quality of life, and also on costs for the health system." (PMID 23171648, 2012).